IFI35 (interferon induced protein 35)
Diseases named in the same sentence as IFI35 in open-access papers (continued):
Sharing a sentence is not in itself a finding about the gene and the disease.
tumor (continued). "In summary, IFI35 is one of interferon-inducible proteins, which is involved in the regulation of tumor cell functions such as cell survival and apoptosis." (PMID 34082779, 2021). "Taken together, these results show that Ifi35 deficiency in immune cells does not affect syngeneic tumor growth." (PMID 38216673, 2024). "As expected, IFI35 was expressed in the cytoplasm of immune cells, tumor cells, and fibroblasts." (PMID 38216673, 2024). "In genetically engineered mouse models proficient or deficient of IFI35, we showed that its deficiency in immune cells does not affect tumor growth." (PMID 38216673, 2024). "However, combination therapy with IFI35 ablation and anti-PD-1 treatment showed a significant reduction in tumor growth and obviously prolonged survival." (PMID 38216673, 2024). "Since tumor-secreted IFI35 could enhance cytotoxicity of CD8+ T cells, we wondered whether IFI35-stimulated CAR-T cells would do better in eliminating tumors." (PMID 37380972, 2023). "Together, these findings suggest that IFI35 is a tumor suppressor in CRC." (PMID 37380972, 2023). "IFI35 caused strong inhibition of tumor growth in immunocompetent mice, but not in nude mice, which suggested that the antitumor effect of IFI35 is immune-dependent." (PMID 37380972, 2023). "Subsequently, we examined the anti-tumor effect of IFI35 in vivo." (PMID 37380972, 2023). "To explore the immune mechanism by which IFI35 may affect tumor growth, we analyzed the immune cell composition in control and IFI35-overexpressing murine tumors by flow cytometry." (PMID 37380972, 2023). "Our results indicated that knockdown of IFI35 could inhibit the tumor progression by enhancing autophagy, indicating that IFI35 could be a potential therapeutic target since it is highly expressed in cancer." (PMID 35740527, 2022). "Moreover, the inhibition of tumor growth by knockdown of IFI35 was abolished in the 3-MA-treated group." (PMID 35740527, 2022). "Likewise, the knockdown of IFI35 also suppressed tumor growth or tumor lung metastasis in these two models." (PMID 35740527, 2022). "In summary, our data suggested that IFI35 maybe a promising novel target that helps to reshape macrophage polarization towards the M1 subtype for anti-tumor effects." (PMID 35844580, 2022). "In addition, IFI35 was an immunoregulatory factor that was also detected in tumor infiltrating immune cells." (PMID 35740527, 2022). "To elucidate the mechanism underlying IFI35 function, we investigated how modifying the IFI35 expression in tumor cell lines and mouse models could influence tumor-inhibition." (PMID 35740527, 2022). "Similarly, the IFI35 knockdown resulted in significant inhibition of tumor progression in the subcutaneous or lung metastasis mouse model." (PMID 35740527, 2022). "Moreover, knockdown of IFI35 inhibited tumor growth rate significantly in the IFI35 knockdown group vs the control group." (PMID 35740527, 2022). "Therefore, the expression of IFI35 in infiltrating immune cells was less likely to interfere with the result detected for IFI35 expression in tumor tissues." (PMID 35740527, 2022). "In addition, the expression of IFI35 was positively correlated in immune and tumor cells." (PMID 38216673, 2024). "In addition, IFI35 ablation obviously inhibited tumor growth and extended survival." (PMID 38216673, 2024). "Moreover, we showed that the CD8+ T cell dependent anti-tumor effect of IFI35 could be explained by its up-regulation of the proliferation and function of CD8+ T cells." (PMID 37380972, 2023). "Therefore we further analyzed the expression of IFI35 in tumor cells from each CMS phenotype." (PMID 37380972, 2023). "We found that IFI35 is positively associated with the activation of CD8+ T cells and predicts a better prognosis in multiple kinds of cancers, thus we hypothesized that IFI35 is involved in regulating the anti-tumor activity of CD8+ T cells." (PMID 37380972, 2023).
tumor (continued). "However, IFI35 autophagy pathway regulation in tumor development is unclear." (PMID 35740527, 2022). "In view of the special structure of IFI35 and characteristics in cells, and since IFI35 is involved in the immune regulation of various diseases and the apoptosis of tumor cells, it could be hypothesized that IFI35 and IRF1 downstream could participate in the radiosensitivity of CRC." (PMID 34082779, 2021). "Collectively, these results indicate that tumor-intrinsic IFI35 drives the infiltration of MDSCs, preventing the actions of effector CD8+ T cells and ultimately accelerating TNBC tumor progression." (PMID 38216673, 2024). "To explore how IFI35 induces an immunosuppressive microenvironment in TNBC, we performed RNA-seq with the Ifi35ko and WT 4T1 tumor cells." (PMID 38216673, 2024). "Also, we explored whether IFI35 or CCL2 affect PD-L1 expression in tumor cells." (PMID 38216673, 2024). "Strikingly, we observed that overexpression of IFI35 promoted CD8+ T cells to secrete more IFNγ and TNFα in CT26 tumor." (PMID 37380972, 2023). "Our data offer valuable insights into the tumor secreted protein, IFI35, which enhances the proliferation and cytotoxicity of CD8+ T cells by activating the PI3K/AKT/mTOR signaling pathway and suppresses tumor growth in a CD8+ T cell-dependent manner." (PMID 37380972, 2023). "IFI35 is an interferon-stimulated gene that is involved with STAT1-mediated cellular proliferation in epithelial cells and tumor cells." (PMID 35740527, 2022). "For the first time, the link between IFI35 and M1 macrophages in TNBC was elucidated, and the anti-tumor role of IFI35 was confirmed." (PMID 35844580, 2022). "In order to determine the function of IFI35 in the pathogenesis of RCC, IFI35 expression was first detected in tumor tissues from TMA slides of patients." (PMID 35740527, 2022). "As a result, it showed that neither IFI35 ablation in WT tumor cells nor CCL2 rescue in Ifi35ko tumor cells affected the expression of PD-L1." (PMID 38216673, 2024). "In addition, IFI35 did not exert a crucial role in immune cells but rather promoted the progression of TNBC in a tumor-intrinsic manner." (PMID 38216673, 2024).
cancer (7 papers, 2011 to 2023). A tumor composed of atypical neoplastic, often pleomorphic cells that invade other tissues. "To explore the potential value of IFI35 in cancer immunotherapy, we examined the impact of IFI35 expression levels on immunotherapy efficacy on a web platform TIDE." (PMID 37380972, 2023). "Further, with the pan-cancer datasets in TCGA, the IFI35 mRNA levels were positively correlated with the CD8+ T cells." (PMID 37380972, 2023). "This study aims to provide a theoretical basis for IFI35 as a potential diagnosis and therapeutic target for RCC or other cancers with high levels of IFI35." (PMID 35740527, 2022). "Up to now, the physiological and pathological functions of IFI35 in the cancer-immune environment are largely unknown." (PMID 37380972, 2023). "Nmi could induce apoptosis; contrarily, IFI35 acts against the proapoptotic effect of Nmi when expressed together; and IFI35 promotes survival, inhibits cell death in some cancers." (PMID 34082779, 2021). "However, the biological significance and function of IFI35 in cancer is still not well understood." (PMID 35740527, 2022). "Collectively, high expression level of IFI35 was positively correlated with CD8+ T cells, a good prognosis and higher efficacy in immunotherapy with cancer patients." (PMID 37380972, 2023). "Therefore, the function of IFI35 has been well elucidated in cell homeostasis and innate immunity, but its biological and pathological roles in cancer are not well characterized." (PMID 35740527, 2022). "While the function of the IFI35 gene is not well-defined, the IFITM proteins have roles in immune cell signaling and adhesion, cancer, germ cell physiology, and bone mineralization." (PMID 24069471, 2013).
IFI35 also shares sentences with these, for which no sentence is quoted: influenza (4 papers); central nervous system demyelinating diseases (3); triple-negative breast carcinoma (2); AIDS (1); asthma (1); Autoimmunity (1); bacterial sepsis (1); Chronic Hepatitis C (1); clear renal cell carcinoma (1); connective tissue disease (1); esophageal squamous cell carcinoma (1); Hepatitis (1); melanoma (1); neurodegenerative disease (1); parasite infection (1); respiratory infection (1); rheumatoid arthritis (1); scrub typhus (1); Sezary syndrome (1); tuberculosis (1).